NOTCH1 (notch receptor 1)
Diseases named in the same sentence as NOTCH1 in open-access papers (continued):
Sharing a sentence is not in itself a finding about the gene and the disease.
cancer (continued). "Briefly, we found 34 somatic alterations, including eight genes recorded in the cancer gene list, and confirmed recurrent NOTCH1 (SNVs 6/9, indels 1/9), KRAS (SNVs 1/9), NRAS (SNVs 2/9), FBXW7 (SNVs 2/9), and MTOR (SNVs 2/9) mutations (Table EV1)." (PMID 29880602, 2018). "More importantly, PTEN gene transcription was regulated by Notch1 signaling pathway activation in various cancers." (PMID 29704427, 2018). "NOTCH1 was downregulated in oral cancer cells to help gamma-secretase inhibitors inhibit the spread of cancer cell proliferation." (PMID 30072869, 2018). "A combination of Notch1 blockade and chemotherapy synergistically reduced chemotherapy-enriched cancer stem cells (CSC)." (PMID 30170559, 2018). "More recently, an exciting interaction with the Notch1 pathway has been unraveled in the context of cancer." (PMID 30564578, 2018). "We observed that NOTCH1 as DEC1 was overexpressed in cancer cell line as compared to normal thyrocytes." (PMID 30158530, 2018). "Notch1 was a direct target of miR-433 and its downregulation inhibited the invasion of cancer cells." (PMID 29104587, 2017). "By cross-talking with many other critical cancer genes and pathways, NOTCH1 plays a fundamental role in cancer pathogenesis." (PMID 28500316, 2017). "γ‐Secretase inhibitors (GSIs) are being actively repurposed as cancer therapeutics based on the premise that inhibition of NOTCH1 signaling in select cancers is therapeutic." (PMID 28539479, 2017). "In cancer cells, NF-κB is an important transcription factor that are activated by many intro-cellular or extra-cellular signals pathways, e.g. Notch-1." (PMID 29190981, 2017). "As a key member of the NOTCH family, NOTCH1 is frequently upregulated in human cancers, including CRC30." (PMID 29180678, 2017). "More recently, Chen and coworkers explored the occurrence and the possible functional implications of NOTCH 1 mutations and NOTCH pathway mutations in ESCC cancer development and progression." (PMID 28930282, 2017). "In terms of major cancer-related proteins among SM-specific hubs, NOTCH1, ARFGEF1, PLD2, and RPTOR were strongly aligned with hallmarks of NSCLC." (PMID 29062084, 2017). "Recently, it has been reported that Notch1 maintained a cancer stem-like phenotype in diffuse type gastric cancer by directly regulating CD133, a stem-like cell marker." (PMID 28881855, 2017). "NOTCH1 was recently found to be related to cancer cell metastasis and the maintenance of cancer stem cells." (PMID 28729728, 2017). "The critical roles of Notch1 have been observed extensively during tumorigenesis and prognosis in a variety of cancers." (PMID 28030818, 2017). "More importantly, we identified that rottlerin-induced anti-cancer activity via inhibition of Notch-1 signaling pathway in CNE1 and CNE2 cells." (PMID 28977931, 2017). "NOTCH1 has been reported to act as a transcriptional activator that plays essential roles in the development of multiple types of cancers." (PMID 28947978, 2017). "miR34 is involved in cancer stem cell self-renewal via regulation of downstream targets Notch1/2 and Bcl-2." (PMID 28881855, 2017). "Recently, Notch1 inhibition has shown to deplete the cancer stem cell population in gastric, breast, and glioma cancers through inhibiting angiogenesis and sensitizing the tumors to chemotherapy." (PMID 29152142, 2017). "Notch pathway is implicated in cancer stem cell (CSC) maintenance and inhibition of Notch1 signaling has been reported to decrease growth of tumorspheres." (PMID 28931897, 2017). "Notch1-induced pathways are involved in cell growth, apoptosis, motility, and invasion in many cancers." (PMID 28507277, 2017).
cancer (continued). "Further work is needed, however, to determine the actual connection of these mutant subgroups with Notch1 signaling and clinically relevant features of cancer patients." (PMID 29136506, 2017). "The structural variations frequently led to disruption of cancer-associated genes (e.g., CDKN2A and NOTCH1) with different mutational mechanisms." (PMID 28930282, 2017). "The uncovered regulation between RET, miR-182 and HES1 clearly points toward new prognostic and therapeutic options by using components of the RET-NF-κB/miR-182-HES1/Notch1 axis as potential key targets to restrict cancer progression." (PMID 28122586, 2017). "Transcript levels of ALK2, the NOTCH ligand JAG1, and NOTCH1 were significantly higher in the malignant tumor group compared to the benign group." (PMID 29259971, 2017). "The PR-specific hubs were involved in Wnt SP, signaling by Notch1 in cancer, telomere maintenance, and transcriptional misregulation." (PMID 28892521, 2017). "The well-documented cancer-related genes NOTCH1, CDKN1A, EGR1, AKT3, TNF, MMP9, and SMARCA4 are located in the center of this newly constructed subnetwork." (PMID 28500316, 2017). "NOTCH1, which encodes a member of the NOTCH family of proteins, has been reported to be an important gene in many human cancers, including ESCC." (PMID 29127303, 2017). "It has been shown the over expression of Notch1 protein in my kinds of cancers, such as skin, lung, and and other caners." (PMID 28950865, 2017). "There is increasing evidence for an important link between the PI3K/AKT/mTOR pathway and NOTCH1 in sustaining the cancer stem cell niche." (PMID 27980227, 2017). "The NOTCH1 signaling pathway plays a crucial role in the maintenance of stemness of normal and cancer stem cells." (PMID 27029061, 2016). "Some recent studies suggest that activation of Notch1 signaling promotes cancer metastasis by stimulating EMT via Snail- or Slug-mediated repression of E-cadherin in cancer cells." (PMID 26716415, 2016). "It would be necessary to identify miRNAs that regulate the expression of Notch-1 for better understanding the mechanism of anti-cancer drug-resistance conferred by CAGE." (PMID 26863629, 2016). "Expression of NOTCH1 and its pathway genes maintains cancer stem-like cells (CSCs) in various tumors, as determined by their ability to form spheroids and expression of molecular markers ALDH1, CD133 and CD44." (PMID 27391340, 2016). "The activation of Notch1 has been found to contribute to the invasion and metastasis of cancer via the EMT." (PMID 27666789, 2016). "Lastly, we also knocked down Notch expression using a Notch1 shRNA-expressing vector (pLK 0.1-shNotch1) in H1299 or HeLa cancer cells." (PMID 26716415, 2016). "A group of scientists pointed out that NOTCH1 acted as a significant part in the maintenance of the cancer stem-like phenotype of diffuse type GC through a RBP-Jƙ binding motif in the 5′ promoter region of CD133 gene." (PMID 27938406, 2016). "Recent evidence supports NOTCH1 signaling in the function of CSCs that has been thought to be responsible for the relapse and metastasis of cancer and can be regarded as a promising target for cancer therapy." (PMID 27108536, 2016). "In PC cells, the tyrosine kinase c-Src directly mediated NOTCH1 and Furin interaction, which regulated carcinogenesis and cancer cell growth." (PMID 27938406, 2016). "A further exploration of this ceRNA crosstalk module found that many protein-coding genes in it were associated with human cancers such as CDK6 and NOTCH1." (PMID 27580177, 2016).
cancer (continued). "Finally, frequent cooccurring mutations NFE2L2, KEAP1, and NOTCH1 in a study on more than four thousand human cancers support the notion that the outcome from aberrant Nrf2–Notch crosstalk by mutations in these genes might specifically enhance tumorigenesis and progression to cancer." (PMID 27847554, 2016). "NOTCH1 expressed in both premalignant and cancer tissues, especially in samples of intestinal metaplasia and well-differentiated intestinal type." (PMID 27938406, 2016). "For example, down regulation of Notch1 provoked inhibition of cell growth and apoptosis in cancer cells." (PMID 26884744, 2016). "In contrast with its controversial roles in the regulation of the cell cycle, it was consistently reported that NOTCH1 promoted cancer cell migration and invasion in vitro." (PMID 27049834, 2016). "Proliferation of cells derived from these cancers can be suppressed by pharmacological inhibition of Notch1." (PMID 27806347, 2016). "On the other hand, the aberrant expression of Notch1 and 3 correlated with cancer progression in EHCC." (PMID 27821106, 2016). "ITCH involved in cancer progression mainly depends on its ability to regulate protein stability and the target proteins including p63, p73, Notch1, Dvl2, RASSF5, and LATS1." (PMID 27642589, 2016). "We show here that, while increased Notch1 exerts a growth suppressing function in both human prostate primary epithelial cells and cancer cells, at the gene expression level it induces genes with opposite functions." (PMID 27384993, 2016). "In both subgroups, there are rare cancer-promoting mutations predicted to activate the PI3K pathway (HRAS, KRAS, PIK3CA, PTEN, and TSC1) and to inactivate the Notch pathway (Notch1 and Notch2)." (PMID 26655088, 2016). "Using coculture of human fetal osteoblasts (hFOB) with cancer cells expressing galectin-3, these authors showed that galectin-3 secreted by cancer cells inhibited osteoblast differentiation, a Notch1-regulated process." (PMID 27242966, 2016). "Following 10 days of incubation in undifferentiating stem cell media, NOTCH1 over expressing NT8e cells showed a higher number of oralspheres with 32% and 0.21% NT8e cells for cancer stem-like cells molecular marker such as ALDH and CD133, respectively." (PMID 27391340, 2016). "Phytoestrogens were demonstrated to have chemopreventive effects on cancer metastasis by inhibiting EMT-associated pathways, such as Notch-1 and TGF-beta signaling." (PMID 27231938, 2016). "And, there is report showed that ectopic miR-34a expression increases sensitivity to doxorubicin by directly targeting NOTCH1 and decreasing cancer stem cell properties." (PMID 27487127, 2016). "Notch1 and Notch3 expression is positively correlated with that of PlexinD1 in patient cancer samples." (PMID 27749937, 2016). "Together, these data indicate that autophagy inhibits Notch1-IC-induced cancer cell migration and tumorigenesis." (PMID 27806347, 2016). "All together, these suggest that in the STIC context, EFEMP1 has a cancer stem cell transforming effect via enhancing both oxidative phosphorylation and aerobic glycolysis, which is consistent with the NOTCH1 up-regulation." (PMID 26307682, 2015). "Hypoxia and HIF-1α are also key to maintenance of cancer cell stemness via Notch1 signaling, and hypoxia induces expression of genes associated with stemness in ovarian cancer." (PMID 26343197, 2015). "Notch-1 promotes invasion and metastasis of cancer cells but its role in salivary adenoid cystic carcinoma (SACC) remains unelucidated." (PMID 25990317, 2015). "On the other hand, resveratrol possesses multifaceted targeting capacities and the cancer-associated signaling pathways mediated by STAT3, Wnt2 and/or Notch1/2 have been known as its molecular targets." (PMID 25896424, 2015). "Specifically, benign prostate cells had the highest levels of Notch1 protein and higher levels of Notch2 protein than three of four cancer lines." (PMID 25864518, 2015).
cancer (continued). "This is in line with the activating effect that EZH2 induces on the NOTCH1 gene, which triggers the expansion of cancer stem cells through a repressive-independent mechanism." (PMID 26029238, 2015). "Lastly, all the 13 NED areas in our sample collection were marked by distinct to strong SOX2 expression, and 11/13 also showed a distinct to strong NOTCH1 expression, involving nearly all cancer cells." (PMID 25686823, 2015). "It has been reported that cyclin D1 and survivin are downstream targets of Notch1 and collectively play a role in chemoresistance in cancer." (PMID 26011160, 2015). "Similar to the expression pattern observed in cancer cells, membranous/cytoplasmic/nuclear Notch1, with an extra-nuclear staining as the major signal, was observed in NSCLC tumors." (PMID 25653136, 2015). "Our findings and those by other investigators suggest that Notch-1 regulates cancer cell growth at least partially by modulating apoptosis of these cancer cells." (PMID 25990317, 2015). "We found that prostate benign cells generally have higher baseline Notch1 and Notch2 expression and more Notch pathway activation than cancer cells." (PMID 25864518, 2015). "Mutation frequency in FAT1, NOTCH1 and CASP8 in HNSCC is significantly higher (p < 0.05) in comparison to other cohorts of squamous or similar cancers." (PMID 26506389, 2015). "More recently, novel Cripto-interacting proteins, also involved in cancer, have been identified including the chaperonin glucose regulated protein-78 (Grp78) and Notch1." (PMID 25629528, 2015). "Our study results emphasize the key role of the Notch1 signaling pathway in regulating EMT via the transcription factor Slug during cancer cell invasion and metastasis, using both in vitro and in vivo models." (PMID 25645291, 2015). "It has been reported that Notch-1 induced EMT and was associated with drug resistance in a variety of human cancers including PC." (PMID 25638153, 2015). "Ginkgolic acid inhibits the formation of the E1-SUMO complex in the SUMOylation process to impair the activation of NOTCH1 in cancer cells." (PMID 25734985, 2015). "Upon Notch1 activation in vitro, a mostly extra-nuclear staining was substantially turned into the nuclear signal in cancer cells." (PMID 25653136, 2015). "Further, the Notch pathway is an important driver in oncogenesis, as activating mutations in Notch pathway components, such as NOTCH1 and NOTCH2, can drive specific cancer types." (PMID 24874471, 2014). "P65 (21 of 30 cases; 70.0%) and Notch1 (15 of 30 cases; 50.0%) were expressed at higher levels in cancer tissues than in non-cancer tissues." (PMID 24970818, 2014). "Changes in the expression of the Notch1 intracellular domain (NICD) and p21 proteins have been shown to be closely associated with the development and progression of a number of cancers." (PMID 24396472, 2014). "Notch1 signaling regulates a wide range of processes in cancer, including cell proliferation, cancer stem cell self-renewal, cell survival, and epithelial–mesenchymal transition." (PMID 25147757, 2014). "Both the upregulation and downregulation of NOTCH1 have been observed in human cancers when compared with normal samples as shown by many study and the Oncomine database." (PMID 25149541, 2014). "More importantly, Notch1 signaling has been shown to be involved in chemoresistance in numerous human cancers." (PMID 24659709, 2014). "Clinical trials have showed promising effect in some cancer patients received treatment with Notch1 inhibitor." (PMID 25477004, 2014). "Several studies strongly support the development of NOTCH1 inhibitors for targeted cancer therapy, particularly for T-ALL, where recurrent NOTCH1 mutations are common and cancer dependency has been well established." (PMID 25072021, 2014). "Both the overexpression and downregulation of NOTCH1 have been observed in human cancers when compared with normal samples." (PMID 25149541, 2014).
cancer (continued). "In this study, we first explored the expression of NOTCH1 in different human cancers in the Oncomine database." (PMID 25149541, 2014). "The studies presented clearly implicate DCLK1 in the regulation of miR-143/145, miR-200, EMT, pluripotency, angiogenesis, NOTCH1, and cancer stemness." (PMID 24040120, 2013). "There is interest in therapeutic targeting of NOTCH1 in cancers in which it has an oncogenic role with antagonists such as inhibitory antibodies and gamma-secretase inhibitors (GSI)." (PMID 23825651, 2013). "For instance, NICD1/CSL transcription complex has been reported to induce EGFR activity and this activation is abolished by NOTCH1 knockdown in other cancers." (PMID 24143218, 2013). "Fixed, paraffin-embedded (FPE) tissues are a potentially rich resource for studying the role of NOTCH1 in cancer and other pathologies, but tests that reliably detect activated NOTCH1 (NICD1) in FPE samples have been lacking." (PMID 23825651, 2013). "Higher levels of both Notch1 and Notch3 RNA expression in the cancer cell lines than that in the Het-1A cell line were repeatedly verified." (PMID 23409141, 2013). "Notch1 signaling can also contribute to the survival of cancer cells by protecting cells from apoptosis because this signaling pathway activates targets involved in cellular survival, such as phosphoinositide kinase-3 (PI3K)/Akt, survivin and Bcl-XL." (PMID 23671619, 2013). "Here, to study the effects of CK2α on cancer stem cell maintenance via regulating Notch1, we first examined CD44 and CD24 expression after treatment with 50 μM CK2α siRNA." (PMID 23651443, 2013). "The majority of studies consider that Notch1 is involved in cancer promotion and, compared with Notch1, there are a small number of studies regarding Notch3." (PMID 23420695, 2013). "Because the activation of Notch1 signaling contributes to the survival of cancer cells, the inhibition of the Notch1 pathway can sensitize cells to chemotherapy." (PMID 23671619, 2013). "Despite these differences, there were significant overlaps in the mutational profiles of the two cancer types, including mutations in the NOTCH receptors (NOTCH1-3), HRAS, and PIK3CA that were seen in both HPV-positive and negative disease." (PMID 23663293, 2013). "Both the Notch-1 and growth factor-c-Src signaling pathways are involved in the progression of tumors in various types of cancer." (PMID 22479394, 2012). "Our finding that knockdown of Notch1 inhibited cancer cell growth are consistent with earlier studies." (PMID 22937170, 2012). "In CSCs from various cancers, there is expression of the key ‘stemness’ genes, Oct-4, Bmi1, Notch1, ALDH1, and Sox2." (PMID 22662215, 2012). "Modulation of both NOTCH1 and NFKB pathways have also been implicated in several cancers including HCC." (PMID 23226395, 2012). "In summary, this study provides support for the combined use of an oncolytic adenovirus and Notch1-siRNA as a promising approach in cancer gene therapy." (PMID 23071601, 2012). "High performance of our resequencing approach is also illustrated by the fact that we identified mutations in known candidate drivers in T-ALL that were included in the collection of known cancer genes such as NOTCH1, FBXW7, PTEN, PHF6, WT1 and PIK3CA." (PMID 22675565, 2012). "Using the Duolink II assay (Olink Bioscience, Uppsala, Sweden), we have shown that endogenous Snail and Notch1 proteins interact in multiple cancer lines (with each red dot in the images representing a fluorescent signal from a Snail-Notch1 interaction)." (PMID 22128911, 2011).